RNU6-743P (RNA, U6 small nuclear 743, pseudogene)
Gene: Small nuclear RNA gene on chromosome 20 (43,405,473 to 43,405,578, forward strand). Ensembl gene ENSG00000201021.
Homologues: Orthologues: chimpanzee U6 (100% identical), macaque U6 (94% identical), pig U6 (78% identical). Paralogues in human: RNU6-15P (87% identical), RNU6-20P (87% identical), RNU6-1145P (86% identical), RNU6-1331P (86% identical), RNU6-166P (86% identical), RNU6-25P (86% identical), RNU6-38P (86% identical), RNU6-41P (86% identical), RNU6-44P (86% identical), RNU6-1 (85% identical), RNU6-11P (85% identical), RNU6-2 (85% identical), and 1286 more.